MIR22 (microRNA 22)
Synonyms: hsa-mir-22; MIRN22; miR-22
Gene: MicroRNA gene on chromosome 17 (1,713,903 to 1,713,987, reverse strand). Ensembl gene ENSG00000283824.
Gene Ontology:
Cellular component: RISC complex
Homologues: Orthologues: chimpanzee ptr-mir-22 (100% identical), guinea pig MIR22 (89% identical), mouse Mir22 (89% identical), pig MIR22 (89% identical), dog MIR22 (88% identical), rat Mir22 (88% identical), macaque MIR22 (86% identical), rabbit MIR22 (86% identical), zebrafish dre-mir-22a (82% identical), tropical clawed frog xtr-mir-22 (72% identical), zebrafish mir22a-2 (69% identical), zebrafish mir22b (66% identical).
Diseases named in the same sentence as MIR22 in open-access papers:
MIR22 is named in the same sentence as 15 diseases in open-access papers, as found by Europe PMC text mining. Sharing a sentence is not in itself a finding about the gene and the disease. The quoted sentences say what the papers report.
acute myeloid leukemia (1 paper, 2021). Acute myeloid leukemia (AML) is a group of neoplasms arising from precursor cells committed to the myeloid cell-line differentiation. "Previous studies in monocytes/macrophages have demonstrated that Mir22 is upregulated through PU.1 during hematopoetic differentiation and a loss of Mir22 is associated with acute myeloid leukemia." (PMID 34423778, 2021).
Alzheimer disease (1 paper, 2022). A progressive, neurodegenerative disease characterized by loss of function and death of nerve cells in several areas of the brain leading to loss of cognitive function such as memory and language. "Mir-22 is involved in spatial memory impairment in Alzheimer’s disease model in mice, and overexpression of Mir-22 protects synaptic structures from degradation and inhibits neuronal apoptosis." (PMID 36613744, 2022).
Glucose intolerance (1 paper, 2020). Glucose intolerance (GI) can be defined as dysglycemia that comprises both prediabetes and diabetes. "Deletion of Mir22 was asymptomatic when mice were bred under standard conditions, except for an onset of glucose intolerance." (PMID 33066497, 2020).
hemangiosarcoma (1 paper, 2016). "Mir-22, which was overexpressed in the hemangiosarcoma samples, has been shown to downregulate PTEN, which parallels the previous finding of PTEN inactivation in canine hemangiosarcoma." (PMID 27912752, 2016).
Hepatic steatosis (1 paper, 2020). Steatosis is a term used to denote lipid accumulation within hepatocytes. "However, when challenged with a high fat-containing diet, Mir22 deficiency dramatically exacerbated fat mass gain, hepatomegaly, and liver steatosis in mice." (PMID 33066497, 2020). "Together these data indicate that MiR22 deficiency in the liver is associated with the upregulation of key factors promoting lipid uptake and glycolysis in the liver, thereby fostering the development of hepatic steatosis in obesogenic conditions." (PMID 33066497, 2020). "In particular, our data demonstrate that genetic deletion of Mir22 triggers body fat accumulation and an exacerbated hepatic steatosis in mice fed an obesogenic diet." (PMID 33066497, 2020).
kidney cancer (1 paper, 2009). Primary or metastatic malignant neoplasm involving the kidney. "In particular, CUL3, over expressed in kidney and prostate cancers, is a target of several dysregulated MIRs: MIR22, MIR23A, MIR23B, MIR218-1, MIR218-2, and MIR301, which are down regulated in kidney cancers, and of MIR22, MIR23A, MIR181A, and MIR181C, which are down regulated in prostate cancers." (PMID 19402918, 2009).
leukemia (1 paper, 2024). A malignant (clonal) hematologic disorder, involving hematopoietic stem cells and characterized by the presence of primitive or atypical myeloid or lymphoid cells in the bone marrow and the blood. "Mir-22 function and regulation appears very complex and, in leukemia, it has been reported to behave either as oncogenic or anti-tumoral depending on the model system." (PMID 38909090, 2024).
lung carcinoma (1 paper, 2020). "MIR22HG (MIR22 host gene) is a tumor suppressor lncRNA involved in proliferation and progression of several types of cancer such as lung cancer." (PMID 32760219, 2020).
Obesity (1 paper, 2020). Accumulation of substantial excess body fat. "To unravel the role of miR-22 in obesity-associated NAFLD, we generated constitutive Mir22 knockout (miR-22KO) mice, which were subsequently rendered obese by feeding with fat-enriched diet." (PMID 33066497, 2020).
tumor (6 papers, 2020 to 2023). "Mir-22 is known to be able to function as a tumour suppressor, and to have neuroprotective function." (PMID 36422592, 2022). "The long noncoding RNA called MIR22 host gene (MIR22HG) was previously identified as a tumor suppressor in several cancers." (PMID 34446703, 2021). "Mir22 can act as either a tumor suppressor or an oncomiR, depending upon the context, and its expression has been shown to increase with aging in hearts." (PMID 34423778, 2021). "For example, Mir-22 and Mir-100 were found to be tumor suppressors in various cancers, including GC." (PMID 32849822, 2020).
infection (1 paper, 2021). The state of being infected such as from the introduction of a foreign agent such as serum, vaccine, antigenic substance or organism. "Cxcl1 and Cxcl2 regulated by Mir22 and Mir155 are chemokines which signal through CXC receptor 2 to attract neutrophils to the place of inflammation, which is essential to control tissue infection." (PMID 34527215, 2021).
MIR22 also shares sentences with these, for which no sentence is quoted: cancer (3 papers); colorectal cancer (1); leprosy (1); prostate carcinoma (1).